AXIN2 (axin 2)
Diseases named in the same sentence as AXIN2 in open-access papers (continued):
Sharing a sentence is not in itself a finding about the gene and the disease.
ovarian carcinoma (16 papers, 2014 to 2025). A malignant neoplasm originating from the surface ovarian epithelium. "Remarkably, the loss of BRCA2 function renders ovarian cancer cells with a more stable β-catenin, and these cells respond to Wnt treatment by preferential upregulation of the negative regulator Axin2." (PMID 39028933, 2024). "The genes BRCA1 e BRCA2 are the strongest recognized genetic risk factors for epithelial ovarian cancer, although some studies show an association with the AXIN2 gene in several cancers, including the ovarian one." (PMID 34378652, 2021). "For example, AXIN2 gene mutations may be implicated in hypodontia along with early-onset colon, prostate, and ovarian cancers." (PMID 39183201, 2024). "Mutations in CTNNB1 (β-catenin) are identified in 16%–54% of endometrioid ovarian cancer patients, and other mutations in APC, AXIN1, and AXIN2, which are key downstream proteins of the Wnt/β-catenin pathway, are also found in different types of ovarian cancer." (PMID 36185280, 2022). "Moreover, CD151-deficient ovarian cancer cells displayed a 2-8-fold increase in β-catenin and Axin-2 proteins, two key signaling intermediates downstream of the canonical Wnt pathway." (PMID 25356755, 2014). "This is the first study to unveil the relationship between TWIST1 and AXIN2 and provides a new perspective to understand the differentiation process of ovarian cancer." (PMID 36123378, 2022). "SFRP4 inhibits Wnt signaling pathway and decreases transcription of Wnt target genes, Axin2, CyclinD1 and Myc, reducing migration ability of ovarian cancer cells by increasing the ability to adhere to collagen and fibronectin." (PMID 33987033, 2021). "Interestingly, BRCA2-null mouse ovarian cancer cells demonstrated a unique response to Wnt3A with the preferential upregulation of the Wnt signaling inhibitor Axin2." (PMID 39028933, 2024). "Nonetheless, it can also be considered that the presence of these truncated Tcf1/7 proteins may be the mechanism preventing the transcription of full-length Tcf1/7, Myc, and cyclin D1 and the preferential transcription of Axin2 instead in the BRCA2-null ovarian cancer cells." (PMID 39028933, 2024). "For example, TFRC, known as the important participant in intracellular iron transport, induced epithelial ovarian cancer (EOC) cell proliferation and metastasis via upregulating the expression level of AXIN2." (PMID 34362387, 2021). "In summary, we found that elevated expression of miR-1207 promoted stem cell-like traits and tumorigenicity in ovarian cancer by simultaneously suppressing multiple inhibitors of Wnt/β-catenin signaling, namely SFRP1, AXIN2, and ICAT." (PMID 26337084, 2015). "Our current study found that SFRP1, AXIN2, and ICAT were targeted and suppressed by miR-1207 in ovarian cancer, which promoted stem cell-like traits through highly activation of Wnt/β-catenin signaling." (PMID 26337084, 2015). "β-catenin downregulation and degradation are observed in non-stem ovarian cancer cells and are positively correlated with TWIST1, which promotes the upregulation of AXIN2, one of the components of the β-catenin destruction complex." (PMID 36123378, 2022). "In the current study, we found that miR-1207 was significantly overexpressed in ovarian cancer and enhanced the stem cell-like traits of ovarian cancer cells by downregulating of multiple negative modulators of the Wnt/β-catenin pathway, including SFRP1, AXIN2 and ICAT." (PMID 26337084, 2015). "Furthermore, we demonstrated that miR-1207 enhanced ovarian cancer stem-like traits through directly targeting SFRP1, AXIN2 and ICAT, which are vital negative modulators of the Wnt/β-catenin pathway." (PMID 26337084, 2015).
craniosynostosis (15 papers, 2013 to 2023). Craniosynostosis is defined as the premature fusion of one or more cranial sutures leading to secondary distortion of skull shape resulting in skull deformities with a variable presentation. "ZBP1 depletion inhibits the expression of RUNX2 and AXIN2, both genes associated with craniosynostosis." (PMID 35627201, 2022). "Axin2 (c.1181G > A, p.R394H, rs200899695) mutation confers susceptibility and perinatal risk factors trigger the occurrence of sagittal craniosynostosis." (PMID 34134783, 2021). "Other groups have found that loss-of-function mutations of AXIN2 will cause excessive ossification in cranial sutures, leading to craniosynostosis in mice and humans." (PMID 34439795, 2021). "We only offered a plausible explanation of Axin2 (c.1181G > A, p.R394H, rs200899695) mutation and perinatal risk factors contribute to sagittal craniosynostosis in a Chinese female monochorionic diamniotic twin family." (PMID 34134783, 2021). "The AXIN2 protein, a negative regulator of Wnt signaling, was previously implicated in calvarial morphogenesis with Axin2 knockout mice showing craniosynostosis." (PMID 29230181, 2017). "We have previously shown that the deletion of Axin2 causes premature suture closure and craniosynostosis in mice." (PMID 26830436, 2016). "Deletion or mutation of Axin2 attribute to craniosynostosis in humans and mice." (PMID 34134783, 2021). "Notably, although homozygous loss of Axin2 can cause craniosynostosis of the interfrontal/metopic suture, heterozygotes were unaffected." (PMID 29752281, 2018). "It will be informative to determine the feasibility and efficacy of this heterogenous suture MSC population in treating craniosynostosis, including Axin2+, Prrx1+, Ctsk+ and CD51+;CD200+ cells." (PMID 35451466, 2022). "Pivotal component mutations in these pathways, including FGFR2 (fibroblast growth factor receptor 2), TWIST1 (twist, drosophila, homolog of 1) and Axin2 (axis inhibitor 2), have been regarded as the origin of craniosynostosis." (PMID 34134783, 2021). "Thus, we speculate that this particular Axin2 mutation leads to haploinsufficiency in female with incomplete penetrance, and additional environmental insults eventually trigger the occurrence of sagittal craniosynostosis." (PMID 34134783, 2021). "Axin2 can inhibit intramembranous bone formation, and the inactivation of Axin2 leads to craniosynostosis because of excessive intramembranous ossification." (PMID 31281389, 2019). "Additionally, Axin2 plays an important role in maintaining suture patency, and the targeted disruption of Axin2 in mice induces malformations of skull structures, a phenotype resembling craniosynostosis in humans." (PMID 37325554, 2023). "Mice deficient in Axin2, a negative regulator of canonical WNT signaling, exhibit craniosynostosis due to an increased proliferation of osteoblastic progenitors in the skull sutures, and haploid deficiency of β-catenin was shown to alleviate craniofacial bone defects caused by Axin2 deficiency." (PMID 34725446, 2022). "Axin2+ SuSC-specific disruption of Bmpr1a in mice, namely, Axin2Cre-Dox;Bmpr1aflox/flox mice, resulted in precocious differentiation and aberrant ossification, leading to craniosynostosis, which initiated at the midline of the suture." (PMID 34439795, 2021). "It has been demonstrated that Axin2 mutant mice present a phenotype resembling craniosynostosis." (PMID 32575385, 2020). "This evidence may confirm that AXIN2 can represent a reliable marker for the stem cell population that undergoes depletion during the premature ossification process occurring in craniosynostosis." (PMID 32575385, 2020). "Mutations in mouse Axin2 and human AXIN2 have been reported to cause craniosynostosis, although the metopic and sagittal sutures and not the coronal are most commonly affected by mutations in these orthologous genes." (PMID 31869306, 2019).
craniosynostosis (continued). "Further studies of clinical samples harvested from patients with craniosynostosis also suggest that Axin 2 may reasonably represent a marker for the stem cell population that undergoes depletion during premature ossification process occurring in craniosynostosis." (PMID 35664558, 2020). "We therefore, have to conclude, that absence of Axin2 does not cause PF-suture craniosynostosis." (PMID 23936395, 2013). "Unlike Gli1+ and Axin2+ SMSCs, the global deletion of postnatal Prrx1+ cells in mice did not lead to craniosynostosis or any other craniofacial phenotype." (PMID 37325554, 2023). "However, increased bone development did not lead to the rescue of all sutures, as the MCAGF8;Axin2+/− mice displayed craniosynostosis of the coronal suture." (PMID 29752281, 2018).
adenoma (14 papers, 2014 to 2025). A neoplasm arising from the epithelium. "One was a 67-year-old patient with 19 adenomas with the mutation c.1994dup p.(Asn666fs) in gene AXIN2 in heterozygosis." (PMID 39661238, 2025). "Differential gene expression analysis of the scRNA-seq data from the adenoma cells showed substantially fewer transcripts encoding the Wnt antagonists Axin2, Dkk2, Dkk3, Wif1, Notum, and Nkd1 in the LApcL mice than in the LApc mice." (PMID 34788095, 2021). "Indeed, serrated adenomas which are enriched for ligand dependent mutations, have lower AXIN2 expression and increased AXIN2 methylation compared to conventional tubulovillous adenomas, as do MSI-high cancers that progress via this pathway." (PMID 33202731, 2020). "Once the serrated adenoma has evolved, additional somatic alterations altering Wnt signaling, such as AXIN2 methylation or frameshift mutation, may contribute to the adenoma’s further growth." (PMID 24964857, 2014). "In three distinct datasets GSE8671, GSE20916 and GSE4183, we recurrently found decreased expression of PRNP transcripts in adenoma versus normal tissue, contrasting with the increase in the expression of several Wnt target genes including AXIN2." (PMID 38589873, 2024). "Four DEGs (MMP-7, MYC, WNT-5A, and AXIN2) were upregulated in tumor vs. normal tissues, or adenoma vs. normal tissue in TCGA, which was overlapped with our data." (PMID 32258125, 2020). "This was accompanied by upregulated expression of Wnt targets Axin2 and Myc in ApcminSh3bp4 cKO adenomas, suggesting that Wnt signaling is hyperactivated upon Sh3bp4 deletion." (PMID 30811977, 2019). "AXIN2 aberrant methylation appears to occur during adenoma growth like MLH1 methylation." (PMID 24964857, 2014). "Upregulation of Axin2 and Snail abundance in APC-MIN adenoma or precancerous sporadic adenoma has been well-reported, and Snail inhibition using anti-sense morpholino suppressed adenoma formation in APC-MIN model." (PMID 28418862, 2017). "ANOVA analysis identified AXIN2, which plays an important role in Wnt signaling pathway cooperating with APC and b-catenin, being more frequently altered in Group 2 that included the serrated adenomas." (PMID 24964857, 2014). "However, overexpression of RAC1B did not increase the number of proliferative cells in the normal small intestine nor in the early adenomas and did not increase the expression of canonical Wnt target genes such as Axin2, Tcf7, Lef1 or Ctnnb1." (PMID 34564693, 2021). "In line with the effect of Ap4 deletion in adenomas, GSEA indicated that mRNAs characteristic for Lgr5-positive ISCs and several factors involved in Wnt/β-catenin and Notch signaling pathways were preferentially downregulated upon deletion of Ap4: for example Sox4, Axin2, EphB3 were downregulated." (PMID 30177706, 2018). "Similarly, Axin2, a classic Wnt target gene, was markedly upregulated in Apc-mutant, but not P-Rspo3, organoids or adenomas." (PMID 28695896, 2017).
pancreatic cancer (13 papers, 2016 to 2026). "Compared to high AXIN2 levels, low AXIN2 levels are associated with the shorter survival of patients with lung and pancreatic cancers." (PMID 41487817, 2025). "In pancreatic cancer, exosomal tRF-19-PNR8YPJZ derived from pluripotent stem cells (PSC) targets AXIN2 in pancreatic cancer cells, reducing its expression and thereby activating the Wnt signaling pathway, which promotes tumor proliferation and metastasis." (PMID 41376858, 2026). "Hypoxia promotes immune escape of pancreatic cancer cells by inhibiting the NK cell miR-1275/AXIN2 axis." (PMID 38035113, 2023). "In conclusion, this research underscores the critical role of the miR-1275/AXIN2 axis in hypoxia-mediated immune escape in pancreatic cancer, thus opening new potential avenues for treatment strategies." (PMID 38035113, 2023). "After induction of NK cells by hypoxia, we determined the NK cell-mediated cancer cell killing ability and investigated the molecular mechanism by which the miR-1275/AXIN2 axis in NK cells inhibits its killing ability against pancreatic cancer cells." (PMID 38035113, 2023). "AXIN2 exhibits high expression within pancreatic cancer NK cells and is negatively modulated by miR-1275." (PMID 38035113, 2023). "We also confirmed the levels of AXIN2, C-myc, and CyclinD1 in excised xenograft tumors originating from pancreatic cancer cells harboring FAM83A knockdown were markedly downregulated." (PMID 36797256, 2023). "Among them, AXIN2 was previously shown to be highly expressed in a variety of tumors, including pancreatic cancer, and plays a tumor-promoting role." (PMID 38035113, 2023). "In summary, we report that the hypoxic environment inhibits miR-1275 expression and thus promotes AXIN2 expression in NK cells, resulting in impaired NK cell killing ability against pancreatic cancer cells and promoting immune escape." (PMID 38035113, 2023). "It has been reported that AXIN2 positively correlates with oncogenic lncRNA FGD5-AS1 expression within pancreatic carcinoma." (PMID 38035113, 2023). "Treatment with BAY ACC002 (30 mg/kg/day for 7 days p.o.)in a Capan-2 pancreatic cancer xenograft mouse model suppressed mRNA expression of the WNT/β-catenin target gene AXIN2 by ∼60% and of the HH target gene GLI1 by 40%." (PMID 27750213, 2017). "In order to evaluate if Axin2 influences the growth of pancreatic cancer we compared the tumor weight in Axin2lacZ/lacZ to the tumor weight in Axin2+/lacZ or Axin2+/+ mice." (PMID 27555909, 2016). "Therefore, we aimed to uncover the mechanism through which hypoxia mediates the immune escape of pancreatic cancer cells, focusing on the influence of miR-1275/AXIN2 on NK cells." (PMID 38035113, 2023). "However, recently, the oncogenic activities of Axin2 have been proposed in various types of cancers, such as breast, colorectal, and pancreatic cancers." (PMID 35875099, 2022). "Mutations that result in the constitutively activated Wnt/β-catenin signal pathways are thought to be related to pancreatic cancer progression. β-catenin is the central effector that mediates the transcription activity of numerous oncogenic target genes, such as C-myc, CyclinD1, and AXIN2." (PMID 36797256, 2023). "Lnc01133 derived from tumor exosomes is highly expressed in both pancreatic cancer cells and their secreted exosomes and can promote pancreatic cancer EMT via the Wnt/β-catenin pathway by silencing AXIN2." (PMID 35819532, 2022). "Treatment of Capan-2, a pancreatic cancer cell line with autocrine WNT and HH signaling, with BAY ACC002, suppressed the expression of the WNT/β-catenin target genes AXIN2, BIRC5, MAD2L1 and OCT4." (PMID 27750213, 2017).
osteosarcoma (11 papers, 2013 to 2025). A usually aggressive malignant bone-forming mesenchymal neoplasm, predominantly affecting adolescents and young adults. "Axin2 transcript levels were significantly increased in osteosarcoma cell lines, compared with the osteoblastic hFOB 1.19 cells." (PMID 34572856, 2021). "In this study, we found that Axin2 and Snail are co-localized in invasive cancer cells within human osteosarcoma tissues and Axin2 is activated in osteosarcoma cell lines compared to human fetal osteoblasts." (PMID 34572856, 2021). "Osteosarcoma sections presented highly co-expressed Axin2 and Snail compared to normal bone tissues." (PMID 34572856, 2021). "To determine the role of the Axin2 in osteosarcoma, we compared the mRNA levels of Axin2 in human osteosarcoma cell lines (MG-63 and SAOS-2) and human fetal osteoblastic hFOB 1.19 cells." (PMID 34572856, 2021). "Within a series of human osteosarcoma tissues, Axin2 usually showed cytoplasmic expression, and Snail expression was mostly found in both the nucleus and cytoplasm of osteosarcoma cells in tumor lesions." (PMID 34572856, 2021). "Niclosamide and pyrvinium suppressed Axin2 and Snail transcript levels in two osteosarcoma cell lines, MG-63 and SAOS-2 cells, at nanomolar concentration, respectively." (PMID 34572856, 2021). "Axin2 and Snail are abundant in patient samples and cell lines of osteosarcoma." (PMID 34572856, 2021). "In order to determine the roles of Axin2 and Snail in clinical samples of osteosarcoma patients, we first detected the protein expression of both Axin2 and Snail by immunohistochemical study in the surgically resected osteosarcoma samples and adjacent normal bone tissues of same patents." (PMID 34572856, 2021). "U2OS osteosarcoma, FIB03 and FIB04 cells were incubated in the presence of control or Wnt3A conditioned medium for 6 h, and the expression of WNT target gene Axin2 was measured by qRT-PCR." (PMID 39043225, 2024). "In this study, we revealed that niclosamide and pyrvinium, known as Wnt inhibitors, effectively target Axin2 and suppress Snail-mediated EMT in osteosarcoma cells." (PMID 34572856, 2021). "In this study, we show that both niclosamide and pyrvinium target Axin2, resulting in the suppression of EMT by the inhibition of the Wnt/Snail axis in osteosarcoma cells." (PMID 34572856, 2021). "Furthermore, we showed that both niclosamide and pyrvinium target Axin2, and effectively induce EMT reversion in osteosarcoma cell lines." (PMID 34572856, 2021). "Axin2 and Snail are candidate therapeutic targets based on EMT for human osteosarcoma." (PMID 34572856, 2021). "We investigated whether Axin2, an important EMT target, could be a suitable molecular target and biomarker for osteosarcoma." (PMID 34572856, 2021). "In this study, we found that Axin2 and Snail are abundant in osteosarcoma patient samples, and both niclosamide and pyrvinium effectively induce the reversion of EMT by suppressing Axin2 and Snail in osteosarcoma cell lines." (PMID 34572856, 2021). "Additionally, the anthelminthic agents niclosamide and pyrvinium, targeting Axin2, may be effective novel EMT therapeutic drugs for patients with osteosarcoma." (PMID 34572856, 2021).